TREM2 (triggering receptor expressed on myeloid cells 2)
Diseases named in the same sentence as TREM2 in open-access papers (continued):
Sharing a sentence is not in itself a finding about the gene and the disease.
Cognitive impairment (continued). "(2019) have confirmed that cGAMP promotes microglial polarisation from M1 towards M2 phenotype by promoting TREM2 expression, and thus ameliorates cognitive impairment, reduces Aβ deposition and neuron apoptosis in AD mice." (PMID 34214019, 2021). "Taken together, our results show that the protective functions of TREM2, both in inflammatory response and cognitive impairment as well as in the decrease of M1 phenotype microglia, are related to PI3K/AKT/FoxO3a signaling pathway in AD mice." (PMID 33065553, 2020). "Overexpression of TREM2 is effective in inhibiting these lesions; water maze experiments have demonstrated that TREM2 overexpression can restore spatial cognitive impairment in mice." (PMID 29655369, 2018). "Based on this evidence and the known role of microglia in clearing α-Syn, we hypothesize that TREM2 enhances microglial clearance of misfolded and aggregated α-Syn in the hippocampus, thereby protecting against cognitive impairment." (PMID 40393958, 2025). "Clinically, elevated levels of soluble TREM2 (sTREM2) in cerebrospinal fluid are associated with attenuated cognitive decline and reduced neurodegenerative risk, particularly among APOE ε4 carriers at the mild cognitive impairment (MCI) stage." (PMID 41373648, 2025). "The Trem2/Dap12 complex recruits spleen tyrosine kinase (SYK) through a cytoplasmic immunoreceptor tyrosine-based activation motif (ITAM), and SYK dysfunction has been shown to be associated with cognitive deficits in AD." (PMID 40234956, 2025). "While the precise molecular interaction mechanisms between these two receptors remain to be fully elucidated, these findings provide novel insights into the pathogenesis of post-mTBI cognitive impairment and highlight the therapeutic potential of dual-targeting p75NTR and Trem2 signaling pathways." (PMID 41574049, 2025). "In addition, Pyrolae herba (PH) regulates TREM2 expression, inhibits LPS-induced neuroinflammation, and alleviates cognitive impairments." (PMID 38627829, 2024). "Furthermore, COG1410 improved long‐term cognitive deficits; however, TREM2 KO abolished these protective effects." (PMID 38649789, 2024). "For example, carriers of the R47H (rs75932628) mutation of TREM2 have higher level of CSF sTREM2 than non-carriers, they display strong association with AD, exhibit early onset and rapid progression of cognitive impairment." (PMID 37240695, 2023). "Outside the retina, a cross-sectional study reported elevated serum levels of the ectodomain of TREM2 in non-obese diabetic patients in comparison with control individuals, which correlates with increased risk of cognitive impairment." (PMID 36869375, 2023). "Short-term exposure of young adult male mice to a soft diet results in dysregulated expression neurodegenerative condition–related genes such as TREM2, DAP12, APOE, and CD33 in the microglia, suggesting that soft diet has an immunomodulatory role as a risk factor for cognitive impairment." (PMID 35764750, 2022). "The changes in musculoskeletal system were present even though the mice expressing TREM2 R47H do not show cognitive deficits and required the presence of additional mutation to increase the appearance of AD-like symptoms [113••]." (PMID 35764750, 2022). "Conversely, type 2 diabetes-related metabolic dysfunction altered microglial TREM2 signaling and resulted in microglial dysfunction, which in turn led to cognitive impairment, thereby suggesting pathological implications of TREM2 in the development of diabetes-related cognitive impairment." (PMID 35592778, 2022). "Since IEC deficiency of Jak3 impacted the cognitive impairment and brain deposition of pTau and Abeta, we determined whether IEC-Jak3 also impacted the TREM2 functions in the brain." (PMID 36145091, 2022).
Cognitive impairment (continued). "In a recent study, it has been shown that TREM2 could be a valuable therapeutic target for the treatment of AD since TREM2 overexpression rescued cognitive impairments in APP/PS1 mice by inhibiting microglia-mediated neuroinflammation." (PMID 35693341, 2022). "TREM2 upregulation had also been determined in peripheral mononuclear cells from AD patients and mild cognitive impairment, implicating that the TREM2 upregulation may be a systemic response of myeloid cells with the progression of AD." (PMID 33557250, 2021). "Damage to axons and dendrites in the vicinity of plaques, termed neuritic dystrophy, is thought to contribute to cognitive impairment in AD and is reported to be enhanced in AD mice lacking Trem2 and humans carrying an R47H allele." (PMID 29859094, 2018). "Additionally, TREM2 Tyr38Cys was found to cause bone mass loss, which could lead to NHD phenotypes that cause cognitive impairment and skeletal deterioration." (PMID 40806186, 2025). "Investigating TREM2-mediated pathological processes in the context of SCI could provide effective strategies for exploring the pathophysiology of cognitive impairment and identifying therapeutic targets as well as developing corresponding drugs for mitigating these often-overlooked deficits." (PMID 41280332, 2025). "Yet again, sensitizing evidence directly connecting TREM2 mutations with post-SCI cognitive impairments is still absent; such linkage currently constitutes an inferred hypothesis based on the mechanistic overlap of AD and SCI." (PMID 41280332, 2025). "We found that most of the activated residential microglia after mTBI were Trem2 positive and p75NTR expression was significantly elevated in Trem2-positive M1-type microglia post-mTBI, correlating with increased pro-inflammatory cytokine release, demyelination, and cognitive deficits." (PMID 41574049, 2025). "Thus, the present study reveals a mechanism by which TREM2 ameliorates cognitive impairment by targeting IFN signaling, which could have significant implications for AD research and prevention." (PMID 38956653, 2024). "Additionally, our findings indicated that increasing TREM2 expression could mitigate long‐term cognitive deficits, while depletion of TREM2 nullified the protective effects of COG1410, consistent with our earlier observations." (PMID 38649789, 2024). "However, we observed that an enriched environment (EE) could ameliorate this cognitive impairment by upregulating microglia TREM2 expression in the hippocampus and suppressing neuroinflammation." (PMID 39758888, 2024). "A series of clinical assessment scales were used to determine if TREM2 p.R47H carriers exhibited differences in depression, anxiety, apathy, fatigue and quality of life compared to the clinical control and mild cognitive impairment group, who did not have the risk variant." (PMID 37990275, 2023). "Nevertheless, although the pathological significance of serum sTREM2 levels in the continuum of cognitive impairment in type 2 diabetes remains unclear, an in vitro study showed that high levels of glucose activated microglia to up-regulate TREM2 expression and induce an inflammatory response." (PMID 35592778, 2022). "In 5xFAD mice, TREM2 knockdown significantly elevates levels of pro-inflammatory cytokines such as IL-1β and TNF-α, exacerbating cognitive deficits." (PMID 40940798, 2025). "However, the role of TREM2 in cognitive impairment in PD remains unclear." (PMID 40393958, 2025). "TREM2 exerts anti-inflammation and neuroprotection, and TREM2R47H induces aberrant activation of cerebral microglia in AD mice, exacerbating cognitive deficits." (PMID 38956653, 2024). "TREM2 has also been demonstrated to attenuate neuroinflammation and neurological damage via Akt/CREB/BDNF signaling as well as ameliorate cognitive impairment and anxiety in a mouse model of traumatic brain injury." (PMID 38956653, 2024).
Cognitive impairment (continued). "In Nondemented individuals with AD neuropathology (NDAN), microglia induced by ePtdSer-TREM2 exhibit enhanced efficiency in clearing damaged synapses, which may underlie the synaptic structural and functional integrity in NDAN individuals, thus preventing cognitive impairment." (PMID 38627829, 2024). "TREM2 activation can reduce neuroinflammation through the PI3K/Akt signaling pathway, which improves postoperative cognitive impairment in mice." (PMID 39408930, 2024). "In addition, new evidence suggests that microglial TREM2 activation reduces microglia-mediated neuroinflammation and ameliorates cognitive impairment via the PI3K/Akt signaling pathway, indicating the TREM2/PI3K/Akt pathway may be a potential neuroprotective target." (PMID 36776829, 2023). "The soluble form of TREM2 (sTREM2) was shown to be increased in the CSF of mild cognitive impairment (MCI) and AD patients compared to controls, probably reflecting a TREM2-dependent microglia response." (PMID 37147668, 2023). "Importantly, a recent report indicated that three proteins, Aβ, TREM2 and Clusterin, display an early increase in patients with severe Aβ pathology but no detectable cognitive defects and in patients with mild cognitive impairment, with continuous accumulation in AD." (PMID 33250918, 2020). "In this study it has been demonstrated that the expression of TREM2 was upregulated in hippocampus of 5xFAD mice, whereas TREM2 knock-out mediated by AAV significantly increased the levels of pro-inflammatory cytokines and aggravated cognitive defect." (PMID 33065553, 2020). "Furthermore, heterozygous TREM2 His157Tyr was also reported in FTD patients, where carriers presented early onset behavioral changes and cognitive impairment." (PMID 40806186, 2025). "Bilberry anthocyanins (BA) lowered serum and brain LPS levels, increased SCFAs in feces, induced microglial phagocytosis of Aβ through the CD33/TREM2/TYROBP signaling pathway, alleviated hippocampal neuroinflammation, and reversed cognitive impairments in APP/PS1 mice." (PMID 38627829, 2024). "Intriguingly, we demonstrated that TREM2 upregulation alleviated cognitive deficits at 3 weeks after TBI which could be mediated by a reduction in WMI, and we once again verified that TREM2 KO could exacerbate neurological behaviours after TBI." (PMID 38649789, 2024). "In our study, none of the TREM2 p.R47H carriers exhibited parkinsonism or reported psychotic symptoms, unlike previous reports from TREM2 p.R47H carriers with cognitive impairment." (PMID 37990275, 2023). "We show that the absence of Trem2 exacerbated cognitive impairments in APP transgenic mice but not in their non-APP littermates." (PMID 32703241, 2020). "Finally, we found that TREM2 can attenuate inflammatory response via the PI3K/AKT/FoxO3a signaling pathway and alleviate cognitive impairment in AD mice." (PMID 33065553, 2020). "We show that the absence of Trem2 exacerbated cognitive impairments in APP transgenic mice but not in their WT littermates." (PMID 32703241, 2020). "Epimedii Folium and Curculiginis Rhizoma, extracts of Horny Goat Weed and Xianmao, enhance TREM2 protein expression in the hippocampus by reducing TNF-α and IL-1β, regulating the transformation and activation of microglial cells, thus improving LPS-induced cognitive impairments." (PMID 38627829, 2024). "Similarly, a recent study reported that long-term voluntary running exercise ameliorated cognitive impairment in APP/PS1 mice by inhibiting TREM2 abscission and maintaining TREM2 protein levels while promoting microglial glucose metabolism and hippocampal morphological plasticity in AD mice." (PMID 35959472, 2022). "We investigated whether serum levels of soluble triggering receptor expressed on myeloid cell 2 (sTREM2), a soluble form of the cell surface receptor TREM2, were predictive of cognitive impairment in type 2 diabetes without obesity." (PMID 35592778, 2022).
Cognitive impairment (continued). "More recently, the AD field has shifted its focus toward molecular targets (e.g., TREM2 and CD33) aimed at preventing β-amyloid and tau pathologies in presymptomatic patients before cognitive impairment occurs or in patients with mild cognitive impairment before irreversible neuronal damage occurs." (PMID 32370229, 2020). "Thus, TREM2 upregulation or IFNAR1 inhibition may serve as an effective treatment for cognitive impairment in patients with various neurological or non-neurological disorders." (PMID 38956653, 2024). "APOE3 carriers show milder cognitive deficits than APOE4 carriers, with preserved microglial Aβ clearance capacity even in the absence of TREM2." (PMID 41168805, 2025). "Interestingly, KO mice lacking the triggering receptor expressed on myeloid cells 2 (TREM2) gene, a risk factor for AD, which protein product regulates the release of cytokines, showed an increase in neuronal and synaptic loss accompanied by cognitive impairment." (PMID 37373230, 2023). "TREM2 mRNA in the dlPFC and PCC was higher in individuals with a clinical diagnosis of AD compared to those with no cognitive impairment (NCI) (p = 0.030, and p = 0.043, respectively) but no different across APOE-ε4 carrier status (p = 0.095 and p = 0.071, respectively)." (PMID 36966244, 2023).
frontotemporal dementia (78 papers, 2013 to 2025). Frontotemporal dementia (FTD) comprises a group of neurodegenerative disorders, characterized by progressive changes in behavior, executive dysfunction and language impairment, as a result of degeneration of the medial prefrontal and frontoinsular cortices. "Mutations in TREM2 increase the risk of late-onset AD and frontotemporal dementia, and microglia deficient in TREM2 have a shortened migration distance to nerve damage and a reduced ability to respond to nerve damage." (PMID 41208869, 2025). "Genome-wide association studies (GWASs) have identified loss-of-function TREM2 variants (e.g., R47H) as significant genetic risk factors for AD, frontotemporal dementia, and Nasu–Hakola disease." (PMID 40940798, 2025). "Subsequent studies have revealed that heterozygous TREM2 mutations have been implicated as risk factors for multiple neurodegenerative diseases, including AD, frontotemporal dementia (FTD), Parkinson's disease (PD), and amyotrophic lateral sclerosis (ALS)." (PMID 38888203, 2024). "Several other TREM2 variants associated with AD and frontotemporal dementia (FTD) have also been found to confer partial loss-of-function, as they impair TREM2 binding to ligands, maturation, ectodomain shedding and microglial phagocytic activity." (PMID 38017562, 2023). "The aim of this study is to investigate the beneficial effects of an advanced neurorehabilitation multimodal approach, including virtual reality, in a patient with fronto – temporal dementia due to TREM2 mutation." (PMID 35623081, 2022). "The aim of this study is to investigate the effects of an advanced neuroRehabilitation protocol using virtual reality in the treatment of a patient with fronto- temporal dementia due to TREM2 mutation." (PMID 35623081, 2022). "Several TREM2 mutations have been identified recently that increase the risk of AD, frontotemporal dementia, PD, and amyotrophic lateral sclerosis." (PMID 26627638, 2015). "The identification that genetic variants in TREM2 are associated with an increased risk of AD and other neurodegenerative diseases, including PD and frontotemporal dementia, has highlighted the role of the immune response in influencing the pathogenesis of these diseases." (PMID 40400621, 2025). "Furthermore, strong genetic links of TREM2 mutations to AD, Frontotemporal Dementia (FTD), Parkinson`s disease (PD) and Amyotrophic Lateral Sclerosis (ALS) have been found." (PMID 36755323, 2023). "Of course, more investigations are needed to confirm the correlation of the described pathways with the TREM2-related loss of functions disease, including frontotemporal dementia, but our approach has aptly demonstrated that it can contribute to managing NHD and other FTD diseases in the future." (PMID 34576123, 2021). "Other TREM2 variants such as Q33X, T66M and Y38C are reported to confer loss of function and have been linked to the development of a frontotemporal dementia (FTD)-like syndrome with early-onset dementia." (PMID 33115519, 2020). "Rare variants in TREM2 strongly increase the likelihood of developing AD, frontotemporal dementia (FTD), Parkinson’s disease (PD) and amyotrophic lateral sclerosis (ALS)." (PMID 31779670, 2019). "In addition to alterations in the trafficking machinery itself, variants in the microglial phagocytic receptor Trem2 that have been associated with neurodegenerative diseases including AD, PD, amyotrophic lateral sclerosis, and frontotemporal dementia impair maturation of this receptor." (PMID 26692002, 2015). "Indeed, recent genetic studies have found that TREM2 mutations represent a significant genetic risk factor in Nasu-Hakola Disease, frontotemporal dementia (FTD), Parkinson’s disease (PD), and amyotrophic lateral sclerosis (ALS)." (PMID 40948752, 2025).